CD99 (CD99 molecule (Xg blood group))
Diseases named in the same sentence as CD99 in open-access papers (continued):
Sharing a sentence is not in itself a finding about the gene and the disease.
tumor (369 papers, 2006 to 2026). "CD99 dysregulation has been observed in various cancers, and the signalling it mediates is significantly associated with tumour cell migration, invasion, metastasis and immune regulation." (PMID 38687049, 2024). "For this reason, the expression of CD99, a membrane glycoprotein marker, serves as a key diagnostic tool in distinguishing between various tumor types." (PMID 39040728, 2024). "The X chromosome breakpoint disrupts the CD99 gene structure, which is associated with a variety of malignant neoplastic diseases, and the gene breakpoint occurs in an AluSc element." (PMID 37117255, 2023). "In the CD99 signaling pathway, GC cells, tumor-associated fibroblasts, and vascular endothelial cells were the primary signal-transducing cells." (PMID 37608794, 2023). "Among our candidates, we also found CD99 to be associated with tumour type and chemotherapy resistance, in addition to OS and PFS." (PMID 33686173, 2021). "Diffuse membranous CD99 immunoreactivity is a hallmark of this tumor and more than 90% of tumors were reported to have EWSR1/FUS-ETS." (PMID 34749732, 2021). "The surface expression of CD99 on ES tumor cells is both a diagnostic marker and potential therapeutic target." (PMID 34133426, 2021). "CD99 has been described as a highly expressed tumor-associated antigen in GBM tissues and a potential target for synthetic multi-peptide vaccines or dendritic cell immunotherapy." (PMID 30845661, 2019). "To define which human CD99 isoform is the main variant present in the tumor vasculature we would need to perform a RT-qPCR on mRNA isolated from by flow cytometry sorted tumor endothelial cells." (PMID 31001265, 2019). "Upregulation of the metalloprotease meprin β and its substrate CD99 is associated with several types of human cancers suggesting functions in tumor development." (PMID 28903388, 2017). "Shang and colleagues demonstrated an association between CD99 overexpression and tumor hypoxia, angiogenesis, epithelial–mesenchymal transition, metabolic reprogramming, and an immunosuppressive microenvironment dominated by M2 tumor-associated macrophages (TAMs)." (PMID 40427525, 2025). "Recently, we found the phenomenon that CD99 CAR-transducing T-ALL cells could cause the tumor cells to kill themselves, and the CAR targeting another antigen expressed on T-ALL cells could result in the same phenomenon." (PMID 37112766, 2023). "Furthermore, CD99 depletion in tumour cells caused redistribution of the actin cytoskeleton and increased activity of the Rho GTPase CDC42, known for its role in actin remodelling and cell migration." (PMID 34374417, 2021). "Additionally, immunotherapy has been demonstrated as another approach, and CD99, a tumor-associated antigen, is a candidate target for this modality of therapy." (PMID 30845661, 2019). "Besides, in the communication analysis between T cell subpopulations and MC subpopulations, we observed that MIF and CD99, key signaling molecules closely associated with tumor immune evasion, are involved in the active communication between T cell and MC subpopulations." (PMID 40932351, 2026). "In tissue stem cells, the high communication activity of CD99 may be associated with cell migration and invasiveness in the tumour microenvironment, promoting tumour cell spread and metastasis, suggesting that XBP1, TRPC6 and TTC28 may promote tumour development." (PMID 40046334, 2025). "In addition, interruption of the CD99:PILRα checkpoint axis may be a relevant therapeutic approach to activate tumor-associated macrophages." (PMID 38534214, 2024).
tumor (continued). "It has been known that CD99 is implicated in various cellular processes including differentiation, apoptosis, homotypic aggregation, and proliferation of lymphocytes, extravasation of leukocytes, transport of several transmembrane proteins, and apoptosis of tumor cells." (PMID 33050232, 2020). "Therefore, the present transcriptome data and the findings of previous studies suggest that extracellular matrix targets, together with tumor-associated antigens, including CD99 and integrins, participate in a cytosolic downstream pathway intermediated by FAK1 and c-Src." (PMID 30845661, 2019). "Therefore, in all these tumors, the downregulation of CD99 protein expression is a critical event in tumor progression and is related to the loss of cellular identity or differentiation and of intercellular adhesion capability with increased migratory/invasion cell capabilities." (PMID 29534016, 2018). "Immunohistochemistry (IHC) showed positivity of the tumor cells for CD99 (cytoplasmic staining of moderate intensity in >50% of the tumor cells) and FLI-1 (nuclear staining of moderate intensity in >50% of the tumor cells)." (PMID 41230381, 2026). "In our previous work, we developed CD99-specific CAR-T cells that exhibited potent antitumor activity against various tumor types, while showing a favorable safety profile with only minimal cytotoxicity toward activated T cells during in vitro culture." (PMID 41596259, 2026). "NV103 is a CD99-antibody targeted irinotecan containing nanoparticle, engineered to selectively deliver irinotecan to CD99 expressing tumor cells." (PMID 41542564, 2026). "Immunohistochemical results revealed that the tumor cells expressed CD99, NKX 2.2, CD117 and vimentin positively, but negatively expressed CK, S-100, CD56." (PMID 41267976, 2025). "Immunohistochemistry showed CK7, EMA, BCL2, and CD99 positivity, paralleling some features of our case, though our tumor was biphasic with predominantly epithelial differentiation and neuroendocrine morphology." (PMID 41393681, 2025). "Researchers have only begun to investigate the possible use of CD99 as a therapeutic target in recent years, leveraging its engagement with monoclonal antibodies to induce cell death in tumor cells that highly express this protein." (PMID 40427525, 2025). "The immunophenotype of this tumor expresses Inhibin, CD99, Calretinin, AE1/AE3, low molecular weight keratin, CD10, Vim, SMA, etc., and rarely expresses EMA." (PMID 40901169, 2025). "Immunohistochemically, the tumor was diffusely positive for CD99, while focally positive for both WT-1 and NKX2.2." (PMID 41426942, 2025). "Recent insights highlight CD99’s role in the communication between tumors and immune cells and with cells within the tumor niche." (PMID 40427525, 2025). "The specific mechanism by which CD99 ligation correlates with cell death in tumor stem cells and blasts while sparing normal HSCs remains somewhat unclear." (PMID 40427525, 2025). "CD99 isoforms have been reported to have opposing functions in mediating inflammation, T cell regulation, tumour cell invasion and migration." (PMID 39810624, 2025). "Immunohistochemistry (IHC) staining of patient tumor sections and immunofluorescence (IF) staining of organoid sections for CD99, VIM, CD68, KI67, and SATB2 showed positive expression in both, confirming histopathological similarities." (PMID 40476445, 2025). "CD99 has been shown to play a role in immune escape, invasiveness, migration, and the adaptability of tumor cells exposed to various stress conditions, including treatment with certain therapeutics." (PMID 40427525, 2025). "In our patient's case, the tumor consisted of small round cells and was CD99+, BCOR+, FLI1+, TLE1−, and NKX2.2−." (PMID 40115314, 2025).
tumor (continued). "The development of multiple anti-CD99 antibodies has shed light on its functions, particularly regarding interactions between tumor cells that overexpress CD99 and immune cells expressing the same protein within the microenvironment." (PMID 40427525, 2025). "In EWS xenografts, anti-CD99 antibody treatment resulted in significant tumor regression and the recruitment of pro-inflammatory macrophages." (PMID 40427525, 2025). "CD99 downregulation is crucial for tumor progression, impacting cellular identity and adhesion, which increases migration and invasion." (PMID 40427525, 2025). "Most studies involving CD99 have historically explored the expression of this antigen in tumors and its potential use as a tumor biomarker for diagnosis and follow-up." (PMID 40427525, 2025). "All of the PDES cell cultures express cell surface CD99 (a protein over-expressed in EWS tumours and used in diagnosis), albeit with greater heterogeneity than the established cell lines." (PMID 41154376, 2025). "Over the years, more evidence has highlighted the dual role of CD99 in immune regulation and tumor progression, suggesting a link between these two functions in the tumor microenvironment (TME)." (PMID 40427525, 2025). "O’Neil and colleagues described similar evidence showing that anti-CD99 antibody treatment induced EWS tumor regression and the recruitment of macrophages." (PMID 40427525, 2025). "CD99 is known to promote T cell infiltration into tumor and co-stimulatory activation, potentially contributing to an immune-hot environment." (PMID 40941002, 2025). "In these instances, CD99 is recognized as an oncogene that enhances cell migration and invasion, leading to tumor cells exhibiting higher metastatic potential." (PMID 40427525, 2025). "The results showed that high-risk tumour cells communicated more actively with multiple cell types, especially in the LAMININ, MK and CD99 signalling pathways." (PMID 40259929, 2025). "Recent studies have highlighted how the triggering of CD99 on M0/M2-like macrophages promotes their polarization toward an inflammatory M1-like phenotype, contributing to tumor killing." (PMID 40427525, 2025). "CD99 ligation induced M2 TAM to M1 reprogramming resulting in reduced tumour growth in patient derived xenografts." (PMID 40442778, 2025). "As this tumor remains incurable in the metastatic, relapsed, and refractory settings, we explored the downstream immune implications of targeting CD99." (PMID 38534214, 2024). "On the other hand, the communication patterns of the target cells suggested that incoming tumor epithelial cell signalings were dominated by mode 1, which included signaling pathways such as CD99 and MK, as well as PTN, CEACAM, CD96, and GRN." (PMID 38482016, 2024). "EwS cell proliferation in vitro and xenograft tumor growth were inhibited when either CD99 or EWS::FLI1 was silenced with DOX, and took off again once DOX was withdrawn, illustrating the independent contribution of both molecules to EwS growth." (PMID 39524141, 2024). "The relevance of prognostic biochemical, histological, and imaging parameters, such as IGF-2 levels, vimentin, CD34, bcl-2, or CD99 positivity but cytokeratin negativity, and tumor size > 10 cm, is unclear." (PMID 39138498, 2024). "ES is characterized by the uniform arrangement of small round bundles or diffuse tumor cells expressing CD99, FLI-1, Ki-67, CD38, and WT-1." (PMID 39139288, 2024). "The involvement of CD99 in the regulation of tumor growth through a specific modulation of FOXM1‐regulated genes involved in G2/M phase offers a core‐set of genes with prognostic value and opens new therapeutic perspectives." (PMID 39524141, 2024).
tumor (continued). "Knock‐down (KD) of both EWS::FLI1 and CD99 significantly impaired EwS cell growth in vitro and tumor growth in vivo." (PMID 39524141, 2024). "When DOX was withdrawn, the expression of EWS::FLI1 and CD99 was rescued, tumor growth restarted and became similar to that of controls." (PMID 39524141, 2024). "Commonly used molecular markers include vimentin, S100 protein and CD99, which collectively assist in determining the cellular origin and genetic lineage of the tumor." (PMID 39483928, 2024). "Inhibition of CD99 in experimental ES is a strategy that can be used to both impair tumor cell viability and promote neural differentiation." (PMID 38785514, 2024). "CD99 is constantly present in EwS cells, known to modulate the EwS genetic profile and tumor malignancy." (PMID 39524141, 2024). "Regarding the input pathways in target cells, the receptors associated with C2 ALOX5+MCs were primarily CD99, SELE, and SPP1, while the receptors related to tumor cells included TWEAK, CEACAM, and CD96." (PMID 39224598, 2024). "The majority of cases are also positive for BCL2 and CD99, and less than half the neoplasms show expression of smooth muscle actin (SMA) and S100." (PMID 39062853, 2024). "Violin diagram showed the interaction between cells, and it was found that the epithelial cell subgroup C3 PLP2+ Tumor EPCs was highly expressed on CD99." (PMID 38482016, 2024). "The tumor cells diffusely expressed CD99, NKX2.2, NKX3.1 and focal expression of CK and EMA was observed." (PMID 38254207, 2024). "Immunohistochemical expression of diagnostic markers EMA, vimentin, NSE and CD99, and AFP was comparable to the expression observed in the primary tumor." (PMID 38201285, 2023). "Immunohistochemical analysis revealed that the tumor cells were positive for CD99/ MIC2, NSE, AE1/ AE3, and FLI-1." (PMID 38065851, 2023). "The CD99 signaling pathway plays an important role in tumor progression and transendothelial migration of cancer cells." (PMID 36647156, 2023). "The EWS tumor cells usually express CD99, vimentin, synaptophysin (Syn), and neuron-specific enolase (NSE) but do not express common antigen (LCA), CD20, and chromaffin granin (CgA)." (PMID 37469664, 2023). "The most important signaling axis in cold tumors was the CD99 signaling axis, and the population receiving this signal was the tumor cell subgroup with the strongest proliferative ability in the late development of cold tumors." (PMID 37120690, 2023). "Positive identification of MID included CD99-positive tumor islets, EWS-FLI1 fusion transcript and EWSR1 rearrangements detected by IHC, RT-qPCR and FISH analysis, accordingly." (PMID 37686475, 2023). "CD99 has been reported to have a marked effect on the migration, invasion and metastasis of tumor cells." (PMID 36776337, 2023). "They primarily communicate with other tumor cells, fibroblasts, and vascular endothelial cells through CD99-CD99 interactions within the CD99 network." (PMID 37608794, 2023). "As it is well known, the expression of SFT markers STAT6, CD34, CD99 and bcl-2 can be lost in most aggressive tumours, following a process of dedifferentiation." (PMID 35864381, 2022). "EWS is a very undifferentiated tumor likely due to overexpression of CD99 protein, which prevents terminal neural differentiation, and EWS-FLI1, which induces aberrant cell differentiation." (PMID 35422060, 2022). "We found CAFs which highly expressed CTHRC1 (from F04 and F08) and tumor associated macrophages were mediated by a different set of ligand-receptor pairs, including THY1/aXb2 complex, GRN/TNFRSF1A, CD99/PILRA, CD74/MIF, APP/CD74, ANXA1/FPR1, etc." (PMID 35928443, 2022). "Conclusively, immunohistochemical (IHC) examination of the markers CD99, S-100, and Ki-67 showed that the tumor cells stained positively for S-100 and CD99." (PMID 35354472, 2022). "A core needle biopsy showed a small, round blue cell neoplasm, (suggestive of a primitive neuroectodermal) stained positive for CD99 and vimentin stain." (PMID 36193025, 2022).
tumor (continued). "In some cancers, the over-expression of CD99 increases migration and invasion, while in most cases, CD99 up-regulation enhances cell–cell adhesion and apoptosis inhibiting tumor cell migration and metastasis." (PMID 35742950, 2022). "In our present study, immunohistochemical staining showed that the tumor cells expressed CD99 in all cases, consistent with the diagnosis of ES/pPNETs." (PMID 34996420, 2022). "IHC staining also showed that tumors treated by AS-8351 had fewer Ki67-positive cells, where the tumor areas were expressed with high CD99." (PMID 35428764, 2022). "Immunohistochemistry showed that tumor cells consistently and diffusely expressed CD99, and expressed Vimentin, Syn and NSE to varying degrees, while CgA a.nd S-100 were often negative." (PMID 36626543, 2022). "STAB2, CD56, and CD99 were scattered positive in few cells in the biopsy tissue, but focal positive in myoid cells in the resected tumor." (PMID 35568949, 2022). "Tumour cells also express CD99, and we have analysed its role in tumour progression and cancer cell TEM." (PMID 34374417, 2021). "Postoperative pathology confirmed that the tumor was a small round-cell malignancy, and the tumor cells were positive for CD99, Friend leukemia virus integration 1 (FLI-1), and neuron-specific enolase (NSE), which was consistent with the diagnosis of a PNET." (PMID 33996888, 2021). "The overexpression of HSPA1A, CD99 and RAB3A showed to be associated with advanced tumour stage, tumour type II, tumour progression, and primary chemotherapy resistance." (PMID 33686173, 2021). "CD99 is also expressed by tumor cells and has a role in tumor progression and cancer cell transendothelial migration." (PMID 33799486, 2021). "CD99 has a pivotal role in ES tumor pathogenesis by regulating tumor cell differentiation and proliferation." (PMID 34133426, 2021). "We confirmed the presence of tumor aggregates within the bone niche in both models and expression of the CD99 EWS marker and found disparities in EWS cell proliferation between bone niches." (PMID 34327193, 2021). "Both control-treated and CD99-depleted tumour cells were detectable in the lungs of most mice 6 h post-injection, and all animals developed lung tumours over the 4 weeks of the assay." (PMID 34374417, 2021). "The vital role of CD99 in ES as well as its paucity of membranous expression in non-tumor cells support CD99 as a therapeutic target." (PMID 34133426, 2021). "SLC25A5 is strongly over-expressed in various types of human cancer cells, while the role of CD99 in cancer is more controversial, since it behaves as an oncogene in most cancers, whereas in some types of neoplasia it behaves as a tumor suppressor gene." (PMID 34360846, 2021). "Such complexity reflects the multistage nature of tumour cell TEM and is consistent with previous findings suggesting either pro- or anti-tumour activity for CD99." (PMID 34374417, 2021). "Flow cytometry for detection of CD45 and CD99 circumvents the need of RT-PCR technique of prior knowledge of EWS fusion oncogene present in the tumor for CTCs analysis." (PMID 34063272, 2021). "Despite seeding less efficiently than the control-treated cells, the CD99-depleted cells showed greater tumour growth in the longer term, with statistically significant differences in luciferase signals observed at the 3- and 4-week time points." (PMID 34374417, 2021). "Immunohistochemically, tumor cells demonstrated membranous positivity for CD99, positivity for Nkx2.2, focal positivity for S100 and negativity for desmin, myogenin, MyoD1, cytokeratin (AE1/AE3), CD31, CD34, CD3, CD20, and CD1a." (PMID 34749732, 2021). "To determine the overall contribution of CD99 expression to metastasis and tumour progression we used an in vivo model." (PMID 34374417, 2021). "We used luciferase-expressing MDA-MB-231 cells, transfected with either control or CD99 siRNA molecules, and assayed tumour burden repeatedly over 4 weeks using in vivo luciferase imaging." (PMID 34374417, 2021).